MOG (myelin oligodendrocyte glycoprotein)
Diseases named in the same sentence as MOG in open-access papers (continued):
Sharing a sentence is not in itself a finding about the gene and the disease.
tumor (continued). "We found that 14/16 MOGAD patients developed neoplasm within 1 year of MOGAD onset, with even higher SIR than at 2 years, although none demonstrated tumor MOG immunostaining." (PMID 39932929, 2025). "Although serum MOG-IgG positivity is rarely observed in non-MOGAD conditions, there are limited reports concerning its association with neoplastic diseases, particularly intracranial tumor." (PMID 41459522, 2025). "In conclusion, concurrent neoplasms were found at a higher frequency than the general population within 2 years of MOGAD onset, but all available tumor tissues were negative for MOG immunostaining suggests that paraneoplastic MOGAD is very rare." (PMID 39932929, 2025). "This suggests that MOG-IgG was not produced by tumor-derived B cells and did not display pathogenicity." (PMID 41459522, 2025). "EGFR and IDH1 were highly expressed in tumor cells, FAP and COL1A1 were confined to fibroblasts, CD68 and ITGAM marked macrophages, PECAM1 and CDH5 identified endothelial cells, OLIG2 and MOG were specific to oligodendrocytes, while CD4 and CD3D defined T-cell subsets." (PMID 41208987, 2025). "Genes critical to oligodendroglial myelination, including myelin-associated glycoprotein (MAG), myelin basic protein (MBP), and myelin oligodendrocyte glycoprotein (MOG), showed significantly decreased expression in tumor tissue following 4-week treatment with the combination." (PMID 38319732, 2024). "Some of them are released in response to an existing tumor, but not restricted to malignancies—as in the case of antibodies against aquaporin-4 and myelin oligodendrocyte glycoprotein (MOG)." (PMID 30524441, 2018). "Of the nine neoplasm tissues obtained, none showed MOG immunostaining." (PMID 39932929, 2025). "Non-tumor components included endothelial cells (expressing VWF, CDH5, ECSCR, SLCO2A1, and MYCT1), pericytes (marked by RGS5, MCAM, and PDGFRB), normal oligodendrocytes (showing PTGDS, MBP, TF, and MOG expression), and TAMs (identified by CD14, AIF1, FCER1G, FCGR3A, TYROBP, and CSF1R)." (PMID 41394801, 2025). "While the association between neoplasms and AQP4-seropositive neuromyelitis optica spectrum disorder (NMOSD) has been investigated in previous studies, data on patients affected by MOG antibody-associated disease (MOGAD) are still lacking and limited on few case reports." (PMID 37360349, 2023). "Ectopic expression of MOG by the patient’s tumor therefore cannot be completely ruled out." (PMID 27802825, 2016). "Moreover, MOG immunostaining was not available in all tumor tissues but only in 9/16 (56%)." (PMID 39932929, 2025). "However, none of the nine tumor tissues obtained demonstrated MOG immunostaining." (PMID 39932929, 2025). "Mice treated with MOG SynNotch-EphA2/IL13Ra2 CAR T cells again showed superior tumor control and survival with no killing detected outside of the tumor in normal brain tissue." (PMID 37754534, 2023).
overlap syndrome (14 papers, 2016 to 2026). "This overlap syndrome is rare and clinically complex, with patients showing concomitant positivity for both MOG and anti-NMDAR antibodies." (PMID 40098969, 2025). "After immune treatment of this overlap syndrome, also MOG titers and MRI findings decreased concurrently with clinical improvement." (PMID 36384491, 2022). "Serum antibodies panel for infectious diseases (including HIV, Herpesviruses, and Borrelia) was unremarkable as well as anti-AQP-4/MOG and connective tissue diseases antibodies." (PMID 36530641, 2022). "Serum anti-AQP-4/anti-MOG and antibodies panel for connective tissue diseases were still unremarkable." (PMID 36530641, 2022). "Overlap syndromes with the occurrence of MOG-IgG in patients with NMDAR encephalitis are a known but rare phenomenon and have been reported only in few patients." (PMID 36384491, 2022). "Instead, the presence of anti-NMDA and anti-MOG antibodies confirmed an overlap syndrome." (PMID 40385909, 2025). "We present the first documented African case of pediatric MOG and NMDAR overlapping syndrome (MNOS), with a review of all pediatric MNOS cases reported thus far in the literature." (PMID 41884830, 2026). "The coexistence of the MOG antibody (MOG-ab) and NMDAR antibody (NMDAR-ab), which is known as the MOG-ab and NMDAR-ab overlapping syndrome (MNOS), is the most common in overlapping syndromes of neural autoantibodies." (PMID 41181155, 2025). "Upon comparing MOG-ON and AQP4-ON patients, significant differences were observed regarding connective tissue diseases (CTDs) and related antibodies." (PMID 38988608, 2024). "Serum anti-AQP-4/anti-MOG antibodies resulted negative as well as connective tissue diseases panel except for the positivity of anti-nuclear antibodies (titer 1:160), considered a non-specific finding." (PMID 36530641, 2022). "Serum anti-AQP-4 and anti-MOG antibodies were negative, as well as an antibody panel for connective tissue diseases." (PMID 36530641, 2022). "Anti-AQP-4/anti-MOG and antibodies for connective tissue diseases were negative." (PMID 36530641, 2022). "Overlap syndrome of triple autoimmune antibodies is rare and the coexistence of antibodies to NMDAR, GABABR and MOG has not been reported till now." (PMID 39877347, 2025).
neurodegenerative disease (10 papers, 2013 to 2025). A disorder of the central nervous system characterized by gradual and progressive loss of neural tissue and neurologic function. "Patients with Lewy body–associated dementia, a neurodegenerative disease, have high levels of autoantibodies against, for example, myelin oligodendrocyte glycoprotein (MOG) and myelin basic protein (MBP)." (PMID 23946635, 2013). "Structural changes in MOG could have implications for neurodegenerative diseases and anti-MOG syndrome." (PMID 39598329, 2024). "Since MOG and MBP fulfill the three criteria outlined in Section “The cause of the cause of degenerative diseases,” these two proteins are candidate pSAgs involved in the autoimmune inflammatory/demyelination of cholinergic neurons in the CNS white matter MS patients." (PMID 28421005, 2017). "We observed a significant reduction in myelination-related genes (e.g., MBP, MOG, PLP1), hence confirming the pathological feature of neurodegenerative diseases." (PMID 39622637, 2025). "The second cluster, consisting of brain and neuronal proteins such as NFL, NFM, NFH, MAP1B, MOG, and MYP0, is termed the neurodegeneration cluster due to the implication of its proteins in neurodegenerative diseases." (PMID 40681694, 2025).
cancer (9 papers, 2016 to 2025). A tumor composed of atypical neoplastic, often pleomorphic cells that invade other tissues. "Among these autoantibodies, those targeting aquaporin-4 (AQP4) and myelin oligodendrocyte glycoprotein (MOG) are associated with a low risk of cancer, even though MOG or AQP4 expression may be detected on cancer tissue, supporting a paraneoplastic origin in those few reported cases." (PMID 37360349, 2023). "In contrast to other neural antibodies, MOG-IgG does not have a strong paraneoplastic association and therefore MOGAD patients should not be routinely screened for cancer." (PMID 35785363, 2022). "All 14 ON patients with malignant tumors included in this study showed negative results in serum tests for pathogens and autoantibodies including antinuclear antibodies, anticardiolipin antibodies, antineutrophil cytoplasmic antibodies, AQP4-Ab and MOG-Ab." (PMID 35222744, 2022).
movement disorder (8 papers, 2018 to 2025). Neurological conditions resulting in abnormal voluntary or involuntary movement, which may impact the speed, fluency, quality and ease of movement. "Amongst these four diseases, LETM and AQP4-IgG are independent risk factors for spinal movement disorders, while MOG-IgG and African American race are associated with a lower risk." (PMID 38977461, 2024).
central nervous system disease (7 papers, 2018 to 2025). "This cross-sectional study examines laboratory and imaging data for patients with demyelinating central nervous system disease to investigate the frequency of MOG-IgA and associated clinical features." (PMID 37548987, 2023).
infectious disease (6 papers, 2020 to 2025). A disorder directly resulting from the presence and activity of a microbial, viral, or parasitic agent in humans. "MOG antibody-positive encephalitic syndromes, when accompanied by normal brain MRI findings, can pose a diagnostic challenge due to their similarity to infectious diseases." (PMID 40078175, 2025).
bacterial infection (5 papers, 2020 to 2026). "However, the absence of these proteins worsens the acute inflammation caused by several stimuli, such as bacterial infection, lipopolysaccharide, or myelin oligodendrocytes glycoprotein- (MOG) induced pro-inflammatory responses." (PMID 36466826, 2022). "Similar to NMOSD and MS, attacks in MOG-EM have been indeed reported to be preceded by viral or bacterial infections (or vaccination) in up to 30% of cases." (PMID 32883348, 2020). "However, postinfectious anti-MOG positive NMO appears after bacterial infections (e.g., B. burgdorferi and Mycobacterium tuberculosis (M. tuberculosis))." (PMID 35624969, 2022).
inflammation (4 papers, 2020 to 2022). Aberrant reaction of the microcirculation characterized by movement of fluid and leukocytes from the blood into extravascular tissues. "Intra-orbital and peri-optic inflammation were more frequently observed in patients with MOG-ON, which was closely related to optic disc swelling and retro-orbital pain provoked by eye movements." (PMID 35615385, 2022). "Exosomal curcumin can repress LPS-induced brain inflammation and myelin oligodendrocyte glycoprotein (MOG)-induced EAE development in mice." (PMID 34675776, 2021).
peripheral neuropathy (4 papers, 2017 to 2023). A disorder affecting the peripheral nervous system. "We present a unique case of EGPA with positive MOG antibodies in the cerebrospinal fluid (CSF) in a patient presenting with peripheral neuropathy." (PMID 38046503, 2023). "The peripheral neuropathy in these cases remains of unclear significance given the exclusive presence of MOG in the CNS in humans, although MOG mRNA transcripts have been detected in the peripheral nerves of rodents and primates." (PMID 35785363, 2022).
retinopathy (2 papers, 2019 to 2023). "In some of these cases, additional antibodies were pathogenically relevant, resulting a complex clinical pictures (e.g., Recoverin antibodies and retinopathy, MOG antibodies and cerebral cortical encephalitis, and LGI1 antibodies and faciobrachial dystonic seizures)." (PMID 37025999, 2023). "In contrast, the retina does not harbor myelin-producing oligodendrocytes and an expression of MOG has not been shown, making a primary retinopathy unlikely." (PMID 31345223, 2019).
CNS tumors (1 paper, 2025). "Subsequent reports of MOGAD or MOG-IgG positivity with concurrent tumors have similarly not shown a clear paraneoplastic relationship with primary CNS tumors." (PMID 41459522, 2025).
nerve ( (1 paper, 2023). "In conclusion, in comparison with the MOG-seronegative ADEM children, MOG-seropositive ADEM children showed lower rates of seizures and cranial nerve (III-XII) palsy with more obvious isolated white blood cell elevations in the blood." (PMID 37274199, 2023).
MOG also shares sentences with these, for which no sentence is quoted: demyelinating diseases of the central nervous system (19 papers); cerebellar ataxia (5); anterior ischemic optic neuropathy (4); immune diseases (4); speech disorder (4); Susac syndrome (4); amyotrophic lateral sclerosis (3); brain tumor (3); cognitive decline (3); Guillain-Barre syndrome (3); idiopathic intracranial hypertension (3); optic atrophy (3); Paralysis (3); zoster (3); acquired immunodeficiency syndrome (2); Acute Hemorrhagic Encephalomyelitis (2); antiphospholipid antibody syndrome (2); autonomic dysfunction (2); brain disease (2); Cerebral atrophy (2); Churg–Strauss syndrome (2); congenital rubella syndrome (2); glaucoma (2); Graves disease (2); hemophilia (2); Hypertension (2); intracranial hypertension (2); ischemic stroke (2); latent infection (2); memory impairment (2).
A further 135 diseases each share a sentence with MOG in 2 papers or fewer.